SYT16 (synaptotagmin 16)
Description:
May be involved in the trafficking and exocytosis of secretory vesicles in non-neuronal tissues. Is Ca(2+)-independent.
Synonyms: STREP14; SYT14L; SYT14R; yt14r; CHR14SYT
Tractability: PROTAC: its protein half-life has been measured.
Gene: Protein-coding gene on chromosome 14 (61,811,849 to 62,112,550, forward strand). Ensembl gene ENSG00000139973.
Subcellular location (Human Protein Atlas): Cytosol
Gene Ontology:
Molecular function: protein binding; phospholipid binding; identical protein binding
Genetic constraint (gnomAD): Loss-of-function variants: 42 observed, 61.29 expected, observed/expected ratio (o/e) 0.69, 90% interval 0.53 to 0.89. The upper end of that interval is the gene's LOEUF score, 0.89, which puts it in group 3 of 6, group 1 being the genes least tolerant of losing a copy. Missense variants: 794 observed, 821.29 expected, observed/expected ratio (o/e) 0.97, 90% interval 0.91 to 1.02. Synonymous variants: 310 observed, 310.81 expected, observed/expected ratio (o/e) 1, 90% interval 0.91 to 1.1.
Homologues: Orthologues: chimpanzee SYT16 (99% identical), macaque SYT16 (98% identical), pig SYT16 (87% identical), rabbit SYT16 (80% identical), rat Syt16 (79% identical), mouse Syt16 (78% identical), dog SYT16 (67% identical), zebrafish syt16 (19% identical). Paralogues in human: SYT14 (38% identical), SYT9 (16% identical), SYT10 (16% identical), RPH3A (16% identical), SYT6 (16% identical), SYT3 (15% identical), SYTL4 (15% identical), SYT17 (15% identical), SYTL5 (14% identical), SYT11 (14% identical), SYT4 (14% identical), SYT1 (13% identical), and 19 more.
Diseases named in the same sentence as SYT16 in open-access papers:
SYT16 is named in the same sentence as 5 diseases in open-access papers, as found by Europe PMC text mining. Sharing a sentence is not in itself a finding about the gene and the disease. The quoted sentences say what the papers report.
glioma (4 papers, 2022 to 2023). A benign or malignant brain and spinal cord tumor that arises from glial cells (astrocytes, oligodendrocytes, ependymal cells). "SYT16, identified through analysis of the TCGA data, was determined to be a glioma prognostic immune biomarker." (PMID 37781198, 2023). "Multivariate analysis showed that SYT16 was a significant prognostic factor for glioma." (PMID 36004367, 2022). "These channels, including P2X, SYT16, and PANX2, have a unique impact on cell types involved in gliomas, including neurons, microglia, and astrocytes." (PMID 37241023, 2023). "Various LGICs, including P2X, SYT16, and PANX2, have the potential to become altered in the pathogenesis of glioma, which can disrupt the homeostatic activity of neurons, microglia, and astrocytes, further exacerbating the symptoms and progression of glioma." (PMID 37241023, 2023). "Bioinformatic analysis of TCGA database revealed that the expression levels of SYT16 in glioma samples were significantly lower than that in normal samples." (PMID 36004367, 2022). "Moreover, SYT16 was only expressed in grade II and grade III glioma and was positively correlated with tumor grade." (PMID 36004367, 2022).
depression (1 paper, 2022). "Regarding SYT16, and the role of telomeres in depression, there is the hypothesis that individuals with depression present a faster rate of shortening." (PMID 36497531, 2022).
malaria (1 paper, 2022). Malaria is a serious and sometimes fatal disease caused by a parasite that commonly infects a certain type of mosquito which feeds on humans. "The analysis revealed two association signals for mild malaria attacks located within the genes SYT16 (synaptotagmin 16) and PTPRM (protein tyrosine phosphatase receptor type M)." (PMID 35646724, 2022).
cardiac disease (1 paper, 2018). "The remaining differentially expressed genes in MuRF1 Tg + hearts after CH exposure associated with alternative splicing (Ptpru, Svopl, Syt16, Ccp110, Jakmip3, Kansl1l) have not been functionally defined in heart and/or cardiac disease to our knowledge." (PMID 30241514, 2018).
tumor (1 paper, 2025). "Additionally, five key genes (SYT16, NCEH1, NXPE3, MB21D2, and DZIP1L) were identified, which simultaneously appeared in A→B compartment switching, TADs, and chromatin loops in tumor samples, with four of these genes located on the q arm of chromosome 3." (PMID 41049290, 2025).